LINC01065 (long independently transcribed non-coding RNA 1065)
Gene: Long non-coding RNA gene on chromosome 13 (53,099,397 to 53,151,914, reverse strand). Ensembl gene ENSG00000237092.
Diseases named in the same sentence as LINC01065 in open-access papers:
LINC01065 is named in the same sentence as 2 diseases in open-access papers, as found by Europe PMC text mining. Sharing a sentence is not in itself a finding about the gene and the disease. The quoted sentences say what the papers report.
fibromyalgia (1 paper, 2023). A chronic disorder of unknown etiology characterized by pain, stiffness, and tenderness in the muscles of neck, shoulders, back, hips, arms, and legs. "Several genes/loci have been reported more than once in CWP, fibromyalgia, and MCP, including EXD3, SLC39A8, AMIGO3/GMPPB/RNF123, C6orf106, FAF1, SLC24A3, and LINC01065/LINC00558." (PMID 37144689, 2023).
cancer (1 paper, 2022). A tumor composed of atypical neoplastic, often pleomorphic cells that invade other tissues. "The strongest association signal for PTSD was found on chromosome 13 (P = 4.79 × 10–20), in a region spanning noncoding mRNAs LINC01065, PCDH8P1, and RN7SL618P as well as olfactomedin 4–encoding gene OLFM4, which takes part in innate immunity, inflammation, and cancer." (PMID 33905376, 2022).